ENSG00000269095 (novel protein)
Gene: Protein-coding gene on chromosome 19 (17,235,940 to 17,255,448, reverse strand). Ensembl gene ENSG00000269095.
Genetic constraint (gnomAD): Loss-of-function variants: 3 observed, 2.47 expected, observed/expected ratio (o/e) 1.21, 90% interval 0.5 to 1.9. That is too few expected variants to judge how well the gene tolerates losing a copy. Missense variants: 73 observed, 49.24 expected, observed/expected ratio (o/e) 1.48, 90% interval 1.23 to 1.79. Synonymous variants: 47 observed, 27.42 expected, observed/expected ratio (o/e) 1.71, 90% interval 1.34 to 1.96.